CRTAP (cartilage associated protein)
Description:
Necessary for efficient 3-hydroxylation of fibrillar collagen prolyl residues.
Synonyms: CASP; LEPREL3; P3H5; OI7
Tractability: Small molecule: a structure with a bound ligand is known. Antibody: UniProt places it where antibodies can reach, with medium confidence; UniProt predicts a signal peptide or a membrane-spanning region; its Gene Ontology location is reachable by antibodies, with medium confidence. PROTAC: ubiquitination databases record sites on it; its protein half-life has been measured.
Gene: Protein-coding gene on chromosome 3 (33,113,956 to 33,147,773, forward strand). Ensembl gene ENSG00000170275.
Subcellular location: Secreted, extracellular space, extracellular matrix
Subcellular location (Human Protein Atlas): Actin filaments; Cytosol; Intermediate filaments; Predicted to be secreted
Pathways (Reactome):
Extracellular matrix organization: Collagen biosynthesis and modifying enzymes
Gene Ontology:
Molecular function: protein binding; collagen binding
Biological process: negative regulation of post-translational protein modification; protein stabilization; collagen fibril organization; protein folding; spermatogenesis
Cellular component: endoplasmic reticulum; extracellular region; endoplasmic reticulum lumen; protein-containing complex
Genetic constraint (gnomAD): Loss-of-function variants: 32 observed, 34.37 expected, observed/expected ratio (o/e) 0.93, 90% interval 0.7 to 1.25. The synonymous counts are far from expectation, so gnomAD's model fits this gene poorly and the ratio says little. Missense variants: 581 observed, 448.75 expected, observed/expected ratio (o/e) 1.29, 90% interval 1.21 to 1.39. Synonymous variants: 232 observed, 185.26 expected, observed/expected ratio (o/e) 1.25, 90% interval 1.12 to 1.4.
Homologues: Orthologues: chimpanzee CRTAP (99% identical), macaque CRTAP (99% identical), guinea pig CRTAP (94% identical), dog CRTAP (94% identical), pig CRTAP (93% identical), rabbit CRTAP (91% identical), mouse Crtap (89% identical), rat Crtap (89% identical), tropical clawed frog crtap (72% identical), zebrafish crtap (65% identical), Caenorhabditis elegans Y73F8A.26 (25% identical). Paralogues in human: P3H4 (52% identical).
Diseases named in the same sentence as CRTAP in open-access papers:
CRTAP is named in the same sentence as 28 diseases in open-access papers, as found by Europe PMC text mining. Sharing a sentence is not in itself a finding about the gene and the disease. The quoted sentences say what the papers report.
osteogenesis imperfecta (21 papers, 2010 to 2025). Osteogenesis imperfecta (OI) comprises a heterogeneous group of genetic disorders characterized by increased bone fragility, low bone mass, and susceptibility to bone fractures with variable severity. "The clinical and functional importance of prolyl 3-hydroxylation became apparent from mutations in the CRTAP gene (cartilage-associated protein) that cause recessive forms of osteogenesis imperfecta." (PMID 34849481, 2021). "In terms of clinical significance, loss of CRTAP causes a pronounced skeletal phenotype in mice and severe osteogenesis imperfecta in humans." (PMID 27119146, 2016). "The complex is comprised of prolyl 3-hydroxylase 1, cartilage associated protein, and cyclophilin B. Mutations have been identified in the genes encoding the complex members in patients with recessive Osteogenesis Imperfecta." (PMID 24465224, 2014). "Type VII osteogenesis imperfecta (OI), caused by recessive CRTAP mutations, is predominantly lethal in the first year of life." (PMID 40214472, 2025). "Genetic alterations of CRTAP are known to cause osteogenesis imperfecta (OI) in an autosomal recessive manner." (PMID 32922437, 2020). "The phenotype of the Crtap-/- mice led to the identification of CRTAP mutations in patients with recessively inherited forms of osteogenesis imperfecta (OI)." (PMID 20485499, 2010). "Osteogenesis imperfecta (OI) types VII, VIII and IX, caused by recessive mutations in cartilage-associated protein (CRTAP), prolyl-3-hydroxylase 1 (P3H1) and cyclophilin B (PPIB), respectively, are characterized by the synthesis of overmodified collagen." (PMID 31171565, 2019). "Mutations in the genes encoding cartilage associated protein (CRTAP) and prolyl 3-hydroxylase 1 (P3H1 encoded by LEPRE1) were the first identified causes of recessive Osteogenesis Imperfecta (OI)." (PMID 24465224, 2014). "Indeed, human mutations in CRTAP cause recessive osteogenesis imperfecta (OI)." (PMID 27119146, 2016). "It was shown that the protein complex responsible for P986 3Hyp formation is made up of prolyl 3-hydroxylase, cartilage associated protein (CRTAP) and cyclophylin B, and that mutations in the genes encoding any one of these proteins can result in recessive osteogenesis imperfecta." (PMID 21559283, 2011). "Mutations in CRTAP (coding for cartilage-associated protein), LEPRE1 (coding for prolyl 3-hydroxylase 1 [P3H1]) or PPIB (coding for Cyclophilin B [CYPB]) cause recessive forms of osteogenesis imperfecta and loss or decrease of type I collagen prolyl 3-hydroxylation." (PMID 20485499, 2010). "Apart from PATJ, the other gene that popped-up during meta-analysis was CRTAP gene which has been previously stated to play an important role in type II and type VII forms of recessive Osteogenesis Imperfecta, a rare form of the disease." (PMID 27651116, 2016). "Moreover, the role of CypB in bone development disorders, notably osteogenesis imperfecta (OI), has been researched: the Choi group found that severe OI develops in CypB KO mice, indicating the importance of the P3H1/CRTAP/CypB complex in collagen formation." (PMID 39045055, 2024). "Since null mutations in either LEPRE1 or CRTAP can result in recessive forms of Osteogenesis Imperfecta (OI) with almost identical features, P3H1 and CRTAP were hypothesized to stabilize each other." (PMID 24465224, 2014).
Rhizomelia (3 papers, 2014 to 2025). Disproportionate shortening of the proximal segment of limbs (i.e. the femur and humerus). "Clinical features resemble the ones described for CRTAP defects, and patients present mostly perinatal lethality and are characterized by rhizomelia." (PMID 41410595, 2025). "CRTAP and P3H1 are mutually supportive in the complex; deficiency of either component causes severe to lethal OI with rhizomelia, classified as OI types VII and VIII, respectively." (PMID 24968150, 2014). "Mice lacking CRTAP present with growth delay, rhizomelia, and severe osteoporosis together with disruption of other connective tissues, including lung and skin." (PMID 34036937, 2021).
Bruck syndrome (2 papers, 2020 to 2025). Bruck syndrome is characterized by the association of osteogenesis imperfecta and congenital joint contractures. "Three patients were identified with mutations in the P3H1, LEPRE, CRTAP, SERPINF1, PLOD2 (Bruck syndrome), TGFB1, and SGMS2 genes (Calvarial Doughnut Lesions with Bone Fragility)." (PMID 39941180, 2025).
osteochondrodysplasia (2 papers, 2024 to 2025). A term referring to disorders characterized by abnormalities in the development of bones and cartilage. "Since CRTAP was first identified as a cartilage protein expressed in hypertrophic chondrocytes and CRTAP deficiency causes an osteochondrodysplasia, differences in both chondrocyte and osteoblasts would be expected." (PMID 40214472, 2025). "The first evidence of an important role of CRTAP in bone was discovered by studies on Crtap-null mice, which developed osteochondrodysplasia with severe osteopenia and decreased osteoid formation." (PMID 39127989, 2024).
breast carcinoma (1 paper, 2024). "Immunohistochemical staining further validated our molecular findings, showing higher expression of P3H1/3 in breast cancer (BC) tissues and increased levels of P3H1 and CRTAP in liver cancer (LIHC) tissues." (PMID 38706607, 2024).
Camurati-Engelmann disease (1 paper, 2021). Camurati-Englemann disease (CED) is a rare, clinically variable bone dysplasia syndrome characterized by hyperostosis of the long bones, skull, spine and pelvis, associated with severe pain in the extremities, a wide-based waddling gait, joint contractures, muscle weakness and easy fatigability. "A total of 7/47 probands suspected with OI carried variants in 6 disease-causing genes, namely, 1 IFITM5, 1 CRTAP, 2 BMP1, 1 PLS3, and 1 COL1A2 (c.432 + 4_432 + 7delAGTA was ignored previously), and 1 case of Camurati-Engelmann disease with pathogenic variants in TGFβ-1, which was misdiagnosed." (PMID 34557487, 2021).
cognitive decline (1 paper, 2024). "Furthermore, additional studies on the link between human brain aging or aging-related cognitive decline and changes in the expression of ASPHD2, BAD, CRTAP, IPW, and ZNF106 which remain elusive, may also be advantageous." (PMID 38428408, 2024).
Cole-Carpenter syndrome (1 paper, 2024). "Mutations within the CRTAP gene locus can lead to Cole-Carpenter syndrome, which is associated with HC." (PMID 38439105, 2024).
Hydrocephalus (1 paper, 2024). Hydrocephalus is an active distension of the ventricular system of the brain resulting from inadequate passage of CSF from its point of production within the cerebral ventricles to its point of absorption into the systemic circulation. "Here, we report a case of severe OI in an infant with symptomatic hydrocephalus harboring novel compound heterozygous CRTAP variants and requiring ventriculosubgaleal (VSG) shunt placement." (PMID 38548746, 2024).
keloid (1 paper, 2022). An irregularly shaped, elevated mark on the skin caused by deposits of excessive amounts of collagen during wound healing. "Some modifying enzymes, which play important roles in the formation of collagen, were also shown to have high expression levels in keloids, including P3H3, P3H4, PLOD1, and CRTAP." (PMID 35435317, 2022).
major depressive disorder (1 paper, 2024). An episode of depression lasting two or more weeks without an intervening episode of mania. "For example, a GWAS of major depressive disorder stratified by sex in two large biobanks, Generation Scotland and UK Biobank, found that the genes CRTAP, GLB1, and TMPPE at chromosome 3p22.3 were significantly associated with major depressive disorder in males, but not in females." (PMID 38790194, 2024).
genetic diseases (2 papers, 2018 to 2020). "Among genes within this region, only two genes, CRTAP and GLB1, have been reported to be associated with genetic diseases, both of which are manifested in an autosomal recessive manner." (PMID 32922437, 2020). "Mutations in CRTAP, P3H1 and P3H2 cause human genetic diseases." (PMID 30417103, 2018).
tumor (2 papers, 2006 to 2024). "Notably, individuals with elevated expression of P3H2, P3H3, and CRTAP exhibited higher resistance to multiple anti-tumor drugs." (PMID 38706607, 2024).
cancer (1 paper, 2024). A tumor composed of atypical neoplastic, often pleomorphic cells that invade other tissues. "Furthermore, our study identified CNVs associated with P3H family genes, with CRTAP showing a significant association in 25 of the 33 cancer types studied." (PMID 38706607, 2024). "The Proline 3-hydroxylase (P3H) family, which includes P3H1, P3H2, P3H3, P3H4, and CRTAP, has garnered attention in cancer research due to its role in hydroxylating proline residues in collagen." (PMID 38706607, 2024).
infection (1 paper, 2016). The state of being infected such as from the introduction of a foreign agent such as serum, vaccine, antigenic substance or organism. "Akin to PATJ, CRTAP overexpression was also found to inhibit DENV-1 or DENV-2 infection compared to vector transfected controls as indicated by the percentage of total infected cells." (PMID 27651116, 2016).
psychiatric disorder (1 paper, 2018). A disorder characterized by behavioral and/or psychological abnormalities, often accompanied by physical symptoms. "Whilst CRTAP and GLB1 have not previously shown association with psychiatric disorders, both genes are members of the CNTN1 PPI subnetwork." (PMID 29317602, 2018).
CRTAP also shares sentences with these, for which no sentence is quoted: bone disorder (1 paper); connective tissue disease (1); COVID-19 (1); Dengue Haemorrhagic fever (1); fibrosis (1); hypophosphatasia (1); liver cancer (1); metabolic disease (1); Obesity (1); Osteopenia (1); osteoporosis (1); tooth ankylosis (1).